UCA1 (urothelial cancer associated 1)
Diseases named in the same sentence as UCA1 in open-access papers (continued):
Sharing a sentence is not in itself a finding about the gene and the disease.
schizophrenia (4 papers, 2019 to 2022). A major psychotic disorder characterized by abnormalities in the perception or expression of reality. "A former study has shown sex-specific dysregulation of HOXA-AS2, Linc-ROR, MEG3, SPRY4-IT1 and UCA1 lncRNAs in patients with schizophrenia." (PMID 35410190, 2022). "We have demonstrated up-regulation of HOXA-AS2, Linc-ROR, MEG3, SPRY4-IT1, and UCA1 in patients with schizophrenia compared with healthy subjects." (PMID 34220567, 2021). "Expressions of HOXA-AS2, MEG3 and UCA1 were correlated with age at disease onset in patients with schizophrenia." (PMID 31484957, 2019). "We also reported correlations between expressions of HOXA-AS2, MEG3 and UCA1 and age at disease onset in patients with schizophrenia." (PMID 31484957, 2019). "As schizophrenia is known as “an adult vascular-ischemic disorder”20, UCA1 might affect the course of this disorder." (PMID 31484957, 2019). "Based on the acknowledged roles of lncRNAs in neurodevelopment, in the current study, we assessed expression of six lncRNAs namely HOXA-AS2, Linc-ROR, MALAT1, MEG3, SPRY4-IT1 and UCA1 in peripheral blood of 60 patients with schizophrenia and 60 healthy subjects." (PMID 31484957, 2019). "While Gomafu, PINT, GAS5, TCONS_l2_00021339, IFNG-AS1, FAS-AS1, PVT1, and TUG1 are among down-regulated lncRNAs in schizophrenia, MEG3, THRIL, HOXA-AS2, Linc-ROR, SPRY4-IT1, UCA1, and MALAT1 have been up-regulated in these patients." (PMID 34220567, 2021). "We selected six lncRNAs namely HOXA-AS2, Linc-ROR, MEG3, SPRY4-IT1, UCA1 and MALAT1 to assess their expression in peripheral blood of patients with schizophrenia and healthy subjects." (PMID 31484957, 2019).
urothelial carcinoma (4 papers, 2015 to 2025). A malignant neoplasm derived from the transitional epithelium of the urinary tract (urinary bladder, ureter, urethra, or renal pelvis). "UCA1 (Urothelial Cancer Associated 1), originally described in urothelial carcinoma, has been implicated in renal injury settings beyond cancer." (PMID 41303683, 2025). "UCA1 expression was increased in various urothelial neoplastic lesions, including urothelial dysplasia, CIS and papillary low-grade and high-grade urothelial carcinomas—each associated with different morphology, pathogenesis and prognostic implications." (PMID 26191476, 2015). "(n=108), found that the expression levels of an exosome lncRNA panel (UCA1-201, UCA1-203, MALAT1 and LINC00355) had high sensitivity and specificity in differentiating urothelial carcinoma from normal samples (92% sensitivity and 91.7% specificity)." (PMID 36203422, 2022).
benign prostate hyperplasia (3 papers, 2017 to 2024). "Our study presents the level of UCA1 in PCa and prostatic hyperplasia using an ISH method." (PMID 28209917, 2017). "SUMO1P3 and UCA1 expression in urine was able to significantly discriminate low grade NMIBC, healthy control and benign prostatic hyperplasia subjects versus high grade NMIBC and MIBC patients." (PMID 38846969, 2024).
colon adenocarcinoma (3 papers, 2021 to 2022). "For example, the Kaplan–Meier plot of lncRNA UCA1 (ncT0201182652) in colon adenocarcinoma shows the association of low- and high-expression levels (bifurcation point is median) with overall survival." (PMID 34464437, 2021).
hypopharyngeal carcinoma (3 papers, 2017 to 2023). Carcinoma, predominantly squamous cell, arising from the epithelial cells of the hypopharynx. "UCA1 upregulation promotes the proliferation, invasion, and survival of hypopharyngeal carcinoma cells." (PMID 37325064, 2023). "Upregulation of UCA1 promotes cell proliferation and invasion in hypopharyngeal carcinoma and predicts poor survival of hypopharyngeal carcinoma patients." (PMID 29516678, 2018).
Infertility (3 papers, 2022 to 2023). "One possible scenario associated with increased infertility in patients with risk haplotypes of UCA1 would be that elevated UCA1 can enhance beta-oxidation in cumulus cells, resulting in the shortage of lipid droplet storage." (PMID 35901079, 2022). "In vivo study by using UCA1 gene knock-out mice may be able to further confirm how UCA1 influences fatty acid metabolism in the reproductive system and infertility development." (PMID 35901079, 2022).
ovarian endometriosis (3 papers, 2020 to 2023). A non-neoplastic disorder characterized by the growth of endometrial tissue in the ovaries. "In ovarian endometriotic tissues, Urothelial Cancer Associated 1 (UCA1) expression was markedly downregulated, and the extent of UCA1 downregulation was positively connected with the severity of ovarian endometriosis." (PMID 37455911, 2023). "Based on these data, it can be concluded that the downregulation of UCA1 is involved in the pathogenesis of ovarian endometriosis and may be a promising diagnostic and prognostic biomarker of this disease." (PMID 36232884, 2022). "Based on these results, authors concluded that UCA1 participates in the pathogenesis of ovarian endometriosis and may be a putative diagnostic and prognostic marker for this condition." (PMID 32850438, 2020). "Compared with healthy controls, serum lncRNA-UCA1 levels were lowered in patients with ovarian endometriosis, and serum UCA1 levels decreased further as the disease progressed." (PMID 36232884, 2022). "UCA1 might be used as a biomarker to evaluate the prognosis and staging of ovarian endometriosis." (PMID 37455911, 2023).
pneumonia (3 papers, 2023 to 2025). An acute, acute and chronic, or chronic inflammation focally or diffusely affecting the lung parenchyma, caused by an infection in one or both of the lungs (by bacteria, viruses, fungi, or mycoplasma.). "In the pneumonia models constructed using ligation and puncture and lipopolysaccharide, the levels of UCA1 are increased, and it can aggravate the development of pneumonia." (PMID 37321562, 2023).
retinoblastoma (3 papers, 2020 to 2024). A malignant tumor that originates in the nuclear layer of the retina. "UCA1 facilitates cell proliferation and inhibits apoptosis in retinoblastoma by activating the PI3K/Akt pathway." (PMID 38426128, 2024). "Overexpression of lncRNA UCA1 has been suggested to increase cell growth and chemo-resistance by inhibiting miR-513a-5p in retinoblastoma cells." (PMID 35949302, 2022).
squamous cell carcinoma (3 papers, 2015 to 2024). A carcinoma arising from squamous epithelial cells. "Interestingly, two long noncoding RNAs associated with barrett's esophagus or squamous carcinoma, AFAP1-AS1 and UCA1, respectively, were also included." (PMID 26158411, 2015).
acute respiratory distress syndrome (2 papers, 2023 to 2025). Progressive and life-threatening pulmonary distress in the absence of an underlying pulmonary condition, usually following major trauma or surgery. "For example, increased level of UCA1 in the blood is associated with an increased risk of acute respiratory distress syndrome in patients undergoing cardiopulmonary bypass, and UCA1 overexpression can worsen acute septic pneumonia by upregulating the expression of EZH2 and suppressing HOXA1." (PMID 37076497, 2023).
diabetes (2 papers, 2016 to 2022). "As the level of UCA1 was lowest at 6–48 h after AMI, those patients were divided into AMI alone group, AMI + hypertension group, and AMI + diabetes group and the level of UCA1 in different groups was analyzed." (PMID 26949706, 2016). "One bioinformatic study focusing on PC in patients with diabetes pointed out that UCA1 was especially tied up with the prognosis of PC in patients with diabetes and could serve as a diagnostic marker." (PMID 35565245, 2022). "We further investigated the influence of hypertension and diabetes on the level of UCA1." (PMID 26949706, 2016). "Interestingly, the levels of plasma UCA1 were decreased at the early state of AMI patients and increased at day 3 after AMI, which was not affected in AMI patient with hypertension or diabetes." (PMID 26949706, 2016).
gastric adenocarcinoma (2 papers, 2022 to 2023). "Then, we assessed the association between the immune infiltration level and the UCA1 expression level in stomach adenocarcinoma using TIMER." (PMID 35794986, 2022). "In addition, overexpression of lncRNA UCA1 protects PDL1 expression from miRNA inhibition and promotes immune escape in gastric adenocarcinoma cells." (PMID 36755298, 2023).
gastric tumor (2 papers, 2015 to 2021). "There was significant UCA1 upregulation in gastric tumor tissues compared with normal margins which was correlated with lymph node involvement, distant metastasis, and advanced tumor stage." (PMID 37303943, 2021). "UCA1 also induced CDDP resistance through EZH2 targeting and PI3K/AKT activation in gastric tumor cells." (PMID 37303943, 2021).
head and neck cancer (2 papers, 2019 to 2025). A primary or metastatic malignant neoplasm affecting the head and neck. "RESULTS: Ectopic UCA1 expression increased cell migration and invasion but reduced the proliferation of head and neck cancer cells." (PMID 41068676, 2025). "METHODS: We used genetic silencing and ectopic expression approaches to examine the effect of UCA1 dysregulation on the proliferation, colony formation, migration, and invasion of head and neck cancer cells in vitro." (PMID 41068676, 2025). "Preliminary data indicate that phosphorylated C/EBPa is directly recruited into the promoter region of lncRNA UCA1 in HA-treated CD44v3high head and neck cancer cells, resulting in lncRNA UCA1 expression." (PMID 31293964, 2019). "Recently, we found that the expression of both cIAP-2 and XIAP appear to be downregulated in head and neck cancer cells treated with anti-lncRNA UCA1 inhibitor." (PMID 31293964, 2019). "Therefore, we believe that the regulation of lncRNA UCA1 expression in head and neck cancer cells is HA-dependent and CD44-specific." (PMID 31293964, 2019). "CONCLUSIONS: We conclude that HIF1A-induced nuclear UCA1 stimulated cell migration and invasion via interacting with PTBP3, increasing lymph node metastasis in head and neck cancer." (PMID 41068676, 2025). "Furthermore, our recent data show that upregulation of lncRNA UCA1 by HA-CD44v3 binding in CD44v3high head and neck cancer cells significantly enhances ROCK-mediated head and neck cancer cell migration and invasion." (PMID 31293964, 2019).
Kaposi's sarcoma (2 papers, 2021 to 2022). A malignant neoplasm characterized by a vascular proliferation which usually contains blunt endothelial cells. "Kaposi’s sarcoma-associated HSV-encoded miRNAs have been shown to affect the expression of host lncRNAs such as Maternally Expressed 3 (MEG3), antisense non-coding RNA in the INK4 locus (ANRIL), and Urothelial Cancer Associated 1 (UCA1) in favor of cancer development." (PMID 35055001, 2022). "Moreover, the elevated UCA1 facilitated the proliferation and migration of Kaposi's sarcoma (KS) cells, which likely contributed to KSHV pathogenesis and tumorigenesis." (PMID 34345210, 2021).
metastasis (2 papers, 2019 to 2021). The spread or migration of cancer cells from one part of the body (where they first appeared) to another. "The UCA1 upregulation has been directly and significantly associated with certain clinicopathological characteristics of GBC patients including tumor size, lymph node metastasis, TNM stage, and poor overall survival time compared to patients with lower levels of UCA1." (PMID 34575316, 2021). "LncRNA LINC00152, HEGBC, MALAT1 and ROR showed a marked correlation with positive lymph node metastasis (LNM), while lncRNA GCASPC, MEG3, LET and UCA1 had the opposite effect." (PMID 31297033, 2019).
myelogenous leukemia (2 papers, 2019 to 2021). "In addition, lncRNA UCA1 was found to be up-regulated in human myeloid leukemia cell lines (K562 and HL60), while knockdown of lncRNA UCA1 inhibited the survival, migration, and invasion of myeloid leukemia cells in vitro and contributed to their apoptosis." (PMID 34777462, 2021).
nasopharyngeal carcinoma (2 papers, 2021). A carcinoma arising from the nasopharyngeal epithelium. "Moreover, UCA1 promotes nasopharyngeal carcinoma cell proliferation, invasion, and migration through modulation of miR-145." (PMID 34238213, 2021).
pancreatic adenocarcinoma (2 papers, 2021 to 2023). "In pancreatic adenocarcinoma, UCA1 overexpression was found to be associated with shorter overall survival, which enabled UCA1 as a prognostic marker." (PMID 34285140, 2021). "Another similar study found that higher expression levels of oncogenic lncRNA AC099850.3, UCA1, and AP005233.2 in pancreatic adenocarcinoma indicate an immunosuppressive state while the protective factors AL513165.1 and PTOV1-AS2 imply an immune status that suppresses cancer." (PMID 37637063, 2023).
papillary thyroid carcinoma (2 papers, 2021 to 2022). "UCA1 can promote carcinogenesis by the Wnt signaling pathway in papillary thyroid carcinoma." (PMID 35949302, 2022).
Parkinson disease (2 papers, 2021 to 2022). A progressive degenerative disorder of the central nervous system characterized by loss of dopamine producing neurons in the substantia nigra and the presence of Lewy bodies in the substantia nigra and locus coeruleus. "From the accumulating evidence, lnc‐UCA1 promotes inflammation in the animal model of Parkinson's disease and polycystic ovary syndrome through the regulation of phosphatidylinositol 3 kinase (PI3K)/protein kinase B (AKT) pathway." (PMID 34850451, 2022).
placental diseases (2 papers, 2021 to 2024). "Among the paradigmatic genes modified connected to placental disorders, we can mention the long non-coding RNA UCA1, upregulated more than 4-fold by the T188N mutant compared to the WT STOX1A." (PMID 38439971, 2024). "Intersecting the deregulated genes allowed to identify two miRNA (mir193b and miR365a) and one long non-coding RNA (UCA1) that are pivotal for trophoblast fusion, and deregulated in placental diseases." (PMID 34055770, 2021).
silicosis (2 papers, 2023 to 2024). Silicosis is a respiratory disease caused by breathing in (inhaling) silica dust. "In the SiO2 dust‐treated mouse silicosis model, the expression of UCA1 is correlated to the presence of silicosis." (PMID 37321562, 2023).
transitional cell carcinoma (2 papers, 2013 to 2020). A malignant neoplasm arising from the transitional epithelium, usually affecting the urinary bladder, ureter, or renal pelvis. "It has been reported that there were up regulations of LINC00355, UCA1-203, and MALAT1 and down regulation of UCA1-201 in urinary exosomes isolated from transitional cell carcinoma (TCC) of bladder compared with controls in Iranian patients." (PMID 31956395, 2020). "For example, the lncRNA Urothelial Cancer Associated-1 (UCA1) has been screened and cloned from the human bladder (transitional cell carcinoma, TCC) cell line BLZ-211." (PMID 24006935, 2013).
vulvar squamous cell carcinoma (2 papers, 2020 to 2025). An invasive squamous cell carcinoma arising from the vulva. "UCA1 expression is associated with tumor stages and lymph node metastasis in vulvar squamous cell carcinoma." (PMID 33050576, 2020). "In vulvar squamous cell carcinoma tissues, UCA1 was highly expressed compared with normal tissues." (PMID 33050576, 2020).
acute leukemia (1 paper, 2021). A clonal (malignant) hematopoietic disorder with an acute onset, affecting the bone marrow and the peripheral blood. "Long non-coding RNA urothelial cancer-associated 1 (UCA1) is involved in the chemo-resistance of diverse cancers, but it is unclear whether UCA1 is associated with the sensitivity of acute leukemia cells to daunorubicin (DNR)." (PMID 33969374, 2021). "The present study provided an evidence to support UCA1 as a promising target for acute leukemia treatment." (PMID 33969374, 2021). "In conclusion, UCA1 up-regulation facilitated the resistance of acute leukemia cells to DNR via the PI3K/AKT pathway by sponging miR-613." (PMID 33969374, 2021). "In sum, UCA1 up-regulation decreased the sensitivity of acute leukemia cells to DNR." (PMID 33969374, 2021). "Nevertheless, the mechanism by which UCA1 regulates daunorubicin (DNR) resistance in acute leukemia remains unclear." (PMID 33969374, 2021). "Consequently, we aimed to survey the function and regulatory mechanism of UCA1 in DNR resistance in acute leukemia." (PMID 33969374, 2021).
adenoma (1 paper, 2019). A neoplasm arising from the epithelium. "The UCA1 ISH signal was localized predominantly in the epithelial cells in adenoma and carcinoma tissue samples." (PMID 31694571, 2019). "Two candidates with the greatest increase in expression in the adenoma-carcinoma transition were further confirmed by qRT-PCR (UCA1, CCAT1) and by ISH (UCA1)." (PMID 31694571, 2019). "UCA1 was upregulated in adenoma and also in CRC samples and a potential interaction was predicted between UCA1 and hsa-miR-1 based on independent algorithms." (PMID 31694571, 2019).
anaplastic thyroid carcinoma (1 paper, 2022). "In addition, many lncRNAs also play a significant role in the regulation of immunity, such as lncRNA UCA1 attenuated the killing effect of cytotoxic CD8 + T cells on anaplastic thyroid carcinoma (ATC) cells through the miR-148a/PD-L1 pathway." (PMID 35359359, 2022).
atrial fibrillation (1 paper, 2025). A disorder characterized by an electrocardiographic finding of a supraventricular arrhythmia characterized by the replacement of consistent P waves by rapid oscillations or fibrillatory waves that vary in size, shape and timing and are accompanied by an irregular ventricular response. "In HF patients with comorbid AF, lncRNA urothelial carcinoma-associated 1 (UCA1) is upregulated in those with atrial fibrillation compared to patients without a history of atrial fibrillation." (PMID 41282471, 2025).
bone cancer (1 paper, 2024). A primary or metastatic malignant neoplasm affecting the bone or articular cartilage. "Among them, lncRNA UCA1 has a critical role in controlling the growth and change of osteoblasts, the transformation of hBMSCs into cartilage cells, and cell growth in bone cancer." (PMID 39156986, 2024).
carcinoma in situ (1 paper, 2015). "The UCA1 test successfully detected all 7 cases of isolated carcinoma in situ and was more sensitive in this particular setting than cystoscopy or urinary cytology." (PMID 26191476, 2015). "Further studies are needed to investigate the role of the UCA1 test in the early detection of carcinoma in situ lesions." (PMID 26191476, 2015).
Cerebral ischemia (1 paper, 2025). Restriction of arterial blood supply to the brain associated with insufficient oxygenation to support the metabolic requirements of the tissue. "In patients after cerebral ischemia, overexpression of lncRNA UCA1 and under expression of miR-18a-5p showed an inverse correlation." (PMID 41245147, 2025). "In patients after cerebral ischemia, the expression of lncRNA UCA1 increased and miRNA-18a-5p decreased." (PMID 41245147, 2025).
cervical adenocarcinoma (1 paper, 2024). An adenocarcinoma arising from the cervical epithelium. "All additional cervical adenocarcinoma cell lines studied, including HEC-1A, Ishikawa3H12, and HEC-1B, exhibited exceptionally high levels of UCA1 expression, particularly the latter." (PMID 38534790, 2024).
chronic heart failure (1 paper, 2022). "For instance, elevated lnc‐UCA1 is related to lower left ventricle ejection fraction and higher national institute of health stroke scale score in chronic heart failure patients and acute ischemic stroke patients, respectively." (PMID 34850451, 2022).
coagulation disorders (1 paper, 2022). "Third, we only explored the effect of exosomal UCA1 on endothelial cells but not proteinuria and coagulation disorders; further studies are needed to determine the potential connection among these processes." (PMID 36160709, 2022).
colorectal adenoma (1 paper, 2019). An adenoma that arises from the colon or rectum. "To date, there has been no data reported about UCA1 expression in colorectal adenoma patients." (PMID 31694571, 2019).